IL4 (interleukin 4)
Diseases named in the same sentence as IL4 in open-access papers (continued):
Sharing a sentence is not in itself a finding about the gene and the disease.
mastitis (24 papers, 2009 to 2025). Inflammation of breast tissue during lactation or postpartum due to an obstructed duct or infection. "Safak, Risvanli, and Asci‐Toraman (2022) found that the IL‐4 level was lower in cows with mastitis caused by Escherichia coli and Staphylococcus aureus compared to healthy animals." (PMID 39792067, 2025). "Greater concentrations of Th2-associated cytokines, such as IL-4 and IL-10, were detected in milk from CM affected women the week before mastitis detection." (PMID 39896819, 2024). "This study looks at expressions of genes, such as IL-4, IL-10, and IFNγ, linked to immune response mechanisms in mastitis." (PMID 35445115, 2022). "However, associated with mastitis, both IL-4 expression and levels in milk were decreased, suggesting further studies." (PMID 35335696, 2022). "The concentration of IL-4 was significantly lower in the milk of cows with Staphylococcal subclinical mastitis compared to control animals, possibly supporting our findings by causative explanation in subclinical and clinical mastitis." (PMID 35335696, 2022). "Similarly, mutation at point 43673888A>G in the STAT5B gene was significantly linked to mastitis-resistance phenotypic traits (IL-4 and SCC)." (PMID 33202860, 2020). "The SCC and levels of generated cytokines (interleukin (IL)-1, IL-2, IL-4, IL-5, IL-6, IL-8, IL-10, and IL-12) in milk increase in both naturally occurring and experimentally induced mastitis." (PMID 40303387, 2025). "Th1/Th2 polarisation shifted towards Th2 due to the increase in IL‐4 and IL‐5 concentrations in NP cows that developed mastitis in the postpartum period." (PMID 39792067, 2025). "Studies have shown that in naturally occurring subclinical mastitis in cows, the intramammary inflammatory response is driven by IL–1α, IL–4, IL–12, IL–17A, and IFN–γ." (PMID 40005889, 2025). "In cases of postpartum diseases, Th1/Th2 polarisation shifted towards Th2 due to the increase in IL‐4 and IL‐5 concentrations in cows that performed NP and developed mastitis in the postpartum period." (PMID 39792067, 2025). "(2017) suggested that IL‐4 levels were significantly increased in cows with subclinical mastitis compared to healthy cows." (PMID 39792067, 2025). "In general mastitis cases, immunoreactivity was more pronounced for IL-4, IL-6, IL-12, IL-13, IL-17A, TNF-α, and IFN-γ." (PMID 39195804, 2024). "In 2017, average concentrations of IL-4, IL-6, and IL-10 in subclinical mastitis milk with CNS were reported as lower than the values from this study." (PMID 39195804, 2024). "This study found significant differences in IL-4 and IL-6 levels in mastitis milk depending on the type of bacterial infection." (PMID 39195804, 2024). "In the current study, the changes in IL-4, IL-6, and IL-10 were consistent with previous experiments, which proves that lentinan is beneficial for reducing subacute mastitis." (PMID 38731317, 2024). "Concomitant CNS in the streptococci mastitis quarter had the highest IL-6 level but the lowest IL-4 level." (PMID 39195804, 2024). "This study aimed to determine the relationships of IL-4, IL-6, and IL-10 in mastitis milk with concurrent infection, bacterial pathogens, SCC, and MDA, an oxidative stress marker." (PMID 39195804, 2024). "Subclinical and clinical mastitis data demonstrate inflammatory responses to intramammary infection driven by IL-1α, IL-4, and IL-17A." (PMID 39195804, 2024). "In contrast, IL-4 gene expression and levels in milk were lower in mastitis animals compared to healthy animals." (PMID 39195804, 2024). "In mastitis cases, immunoreactivity was more pronounced for IL-4, IL-6, IL-12, IL-13, IL-17A, TNF-α, and IFN-γ." (PMID 35335696, 2022). "Inflammatory cytokine interleukin (IL-10), IL-4, and interferon-gamma (IFNγ) expression genes were measured and compared in mastitis-free and mastitis-affected animals." (PMID 35445115, 2022). "Compared to cows infected with clinical mastitis, healthy cows had higher expression of IL-4 and IFNγ genes (p < 0.0001)." (PMID 35445115, 2022).
mastitis (continued). "Data about subclinical and clinical mastitis demonstrate inflammatory responses to intramammary infection driven by IL-1α, IL-4, and IL-17A." (PMID 35335696, 2022). "The expressions of IL-10, IL-4, and IFNγ genes were contrasted in mastitis-free and mastitis-affected animals." (PMID 35445115, 2022). "These genes are strong predictors of mastitis in the states analyzed, as evidenced by the differential expression in mastitis and healthy conditions of the IL-4, IL-10, and IFNγ genes." (PMID 35445115, 2022). "In cows with mastitis, the expressions of IL-4 and IFNγ genes were significantly lower than those in healthy animals (p < 0.0001)." (PMID 35445115, 2022). "In subclinical mastitis-affected cows, the highest means of immunoreactive cell counts were observed for IL-4 and IL-17A." (PMID 35335696, 2022). "The mean value (%) of IL-4 immunoreactive cell numbers on day 4 was statistically significantly lower in clinical mastitis-affected cows vs. healthy cows (p = 0.006)." (PMID 35335696, 2022). "Compared to cows diagnosed with clinical mastitis, the IL-4 and IFNγ genes were expressed more strongly in healthy cows (p> < 0.0001)." (PMID 35445115, 2022). "On day 5, a mean value (%) of IL-4 immunoreactive cell count was statistically significantly lower in subclinical mastitis-affected cows than in healthy cows (p < 0.001) and clinical mastitis-affected cows (p = 0.026)." (PMID 35335696, 2022). "These preliminary data suggest that determination of IL-1α, MIP-1α, IL-4 in sheep milk samples could contribute to the diagnosis of subclinical mastitis." (PMID 41560862, 2025). "The higher concentrations of IL-4 and IL-6 in the infected quarters in this study might be due to chronic mastitis in the farms with mastitis control problems." (PMID 39195804, 2024). "This study examines the correlation between interleukin-4 (IL-4), interleukin-6 (IL-6), and interleukin-10 (IL-10) levels in mastitis milk and concurrent infections, bacterial pathogens, somatic cell counts (SCCs), and malondialdehyde (MDA), an oxidative stress marker." (PMID 39195804, 2024). "Therefore, this study aimed to determine the relationships of IL-4, IL-6, and IL-10 in mastitis milk with concurrent infections, bacterial pathogens, SCC, and oxidative stress." (PMID 39195804, 2024). "Together, data about naturally occurring subclinical and clinical mastitis demonstrate inflammatory responses to intramammary infection driven by IL-1α, IL-4, IL-12, IL-17A, and IFN-γ in subclinical mastitis, and IL-1α, IL-4, IL-6, and IL-17A in clinical mastitis." (PMID 35335696, 2022). "This might be crucial to hold readiness for both inflammation risk and tissue damage in healthy cows by both IL-4 and IL-13, but only by IL-4 in mastitis-affected cows." (PMID 35335696, 2022). "Mastitis caused by Gram-positive and Gram-negative bacteria was used to assess the expressions of IL-4, IL-10, and IFNγ genetic features connected to the immune system response pathways to mastitis." (PMID 35445115, 2022). "Mastitis-affected ewes had considerably higher levels of IFN-γ, IL-4, TNF-α, MYD88, CCL5, TLR4, TLR9, LTF, and PRLR gene expression than resistant ones." (PMID 40542007, 2025). "Levels of IFN-γ, IL-4, TNF-α, MYD88, CCL5, TLR4, TLR9, LTF, PRLR, Keap1 and OXSR1 genes expression were significantly up-regulated in ewes affected with mastitis than resistant ones." (PMID 40542007, 2025). "Both experimentally induced or naturally occurring mastitis results in an increase in the somatic cell count (SCC) and levels of produced cytokines (interleukin (IL) IL-1, IL-2, IL-4, IL-5, IL-6, IL-8, IL-10, and IL-12) in milk." (PMID 35335696, 2022). "Comparison of the relative gene expressions of IL-10, IL-4, and IFNγ in animals with and without mastitis and the respective significance level of the means." (PMID 35445115, 2022).
mastitis (continued). "In summary, in clinical mastitis-affected cows, immunoreactive cell mean counts in milk increased for IL-4, IL-6, IL-12, and IL-17A and remained nearly absent for IL-13." (PMID 35335696, 2022). "The interactions of polymorphisms in JAK2 with bovine mastitis resistance phenotypic traits (IL-17, IL-6, IL-4, IFN-γ, SCS, and SCC) show that JAK2 might be considered a useful marker in bovine mastitis resistance strategies." (PMID 33202860, 2020). "For Gyr cows, expression of the IL-4 gene showed a trend to be lower in cows with mastitis compared to healthy animals, but this difference was not significant (p < 0.10)." (PMID 21637453, 2009). "In order to characterize the expression of genes associated with immune response mechanisms to mastitis, we quantified the relative expression of the IL-2, IL-4, IL-6, IL-8, IL-10, IFN-γ and TNF- α genes in milk cells of healthy cows and cows with clinical mastitis." (PMID 21637453, 2009). "Therefore IFN-γ immunoreactive mean numbers were lower in subclinical mastitis and almost absent in clinical mastitis, suggesting IL-4 antagonist activity over INF-γ in mastitis conditions." (PMID 35335696, 2022). "Additionally, the observed downregulation of IL-4 and IL-2 following SA infusion in SCM cows indicates that its immunomodulatory effects primarily enhance immune cell phagocytic activity rather than antibody production, which has a limited role in aiding mastitis recovery." (PMID 40564979, 2025). "The cytokines in serum such as interleukin-4 (IL-4), IL-6, IL-17, tumor necrosis factor-α (TNF-α) and interferon-γ (IFN-γ) also act as indirect indexes in inflammatory conditions, which suggests that beside SCC and SCS, serum cytokines could be considered as crucial indicators for bovine mastitis." (PMID 28101335, 2017). "No significant change in gene expression of IL-2, IL-4, IL-6, IL-8, IL-10, IFN-γ, and TNF-α by real-time PCR in milk among animals without mastitis vs. animals with mastitis was observed." (PMID 35335696, 2022). "In the current investigation, qRT-PCR was used to measure the levels of antioxidant (CAT, GPX1, Keap1, OXSR1, ATOX1, GST, and Nrf2) and immune (IFN-γ, IL-4, TNF-α, MYD88, CCL5, TLR4, TLR9, LTF, and PRLR) genes in Barki ewes that were resistant and non-resistant to mastitis." (PMID 40542007, 2025). "It should be emphasized that the IL-4, IL-6, IL-8 and TNF-α genes were not differentially expressed in any of the conditions studied (p > 0.05), demonstrating that these genes are not good markers or indicators of mastitis under the analyzed conditions." (PMID 21637453, 2009). "For this purpose, the expression of the interleukin 2 (IL-2), IL-4, IL-6, IL-8, IL-10, interferon gamma (IFN-γ) and tumor necrosis factor alpha (TNF-α) genes was investigated in Black and White (BW) Holstein and Gyr cows with and without clinical signs of mastitis." (PMID 21637453, 2009).
preeclampsia (24 papers, 2010 to 2025). Preeclampsia is a hypertensive disorder of pregnancy that is characterized by new-onset hypertension with proteinuria presenting after 20 weeks of gestation, and depending on mild or severe forms may initially present with severe headache, visual disturbances, and hyperreflexia. "Low IL-4 levels have been associated with adverse outcomes such as preterm birth, spontaneous abortion, fetal growth restriction, preeclampsia, and recurrent miscarriage." (PMID 41450943, 2025). "We found that the VNTR polymorphism of IL-4 gene has significantly increased the risk of preeclampsia (RP2/RP1 versus RP1/RP1, OR, 2.8 [95% CI, 1.7 to 8.8]; P = 0.0001 and RP2/RP2 versus RP1/RP1; P = 0.002)." (PMID 24877103, 2014). "The results showed that carriage of IL-4 VNTR RP2 allele has positive association with preeclampsia susceptibility." (PMID 24877103, 2014). "Therefore, the present study aimed to study the relationship between preeclampsia risk and rs2069740 (T to A exchange) and rs34255686 (C to A exchange) polymorphisms of IL-13 while evaluating the expression patterns of IL-13 and IL-4 pathway genes in this disease." (PMID 37238928, 2023). "We observed an upregulation in interferon-gamma expression and a downregulation in transforming growth factor-beta-1 (TGF-β1), IL-4, and IL-10 in the placenta of patients with preeclampsia." (PMID 38894741, 2024). "This study applied the second method and used two deep learning algorithms to diagnose preeclampsia based on IL-4 and IL-13 pathway expression patterns." (PMID 37238928, 2023). "IL-4 and IL-13 pathways can considerably affect preeclampsia and deep learning models based on these pathway genes predicting patients’ status with high accuracy." (PMID 37238928, 2023). "In addition, deficiencies in IL-4 and IL-10 cytokines have been associated with a plethora of pregnancy-related disorders, including infertility, spontaneous miscarriage, preterm birth, fetal growth restriction, pre-eclampsia, gestational hypertension, and as we have just demonstrated with CVD." (PMID 36012236, 2022). "In conclusion, we have demonstrated that a set of cytokines, IL-22, MDC, and IL-2/IL-4 can be used to diagnose preeclampsia, and what’s more to discriminate from gestational hypertension." (PMID 34248946, 2021). "The in-depth analysis showed that the IL-22, MDC, and IL2/IL-4 ratio can be used to discriminate between preeclampsia, gestation hypertension and healthy pregnancy." (PMID 34248946, 2021). "Using a diagnostic test assessment characteristic parameters (IL-22, MDC/CCL22, IL-2/IL-4 ratio) have been identified and cut-off values have been proposed to diagnose preeclampsia." (PMID 34248946, 2021). "It is also of note that some markers in the final model—namely FGF-basic and IL-4 exhibited a particularly large influence on the PTB ± preeclampsia algorithm while also having large observed confidence intervals in initial multivariate logistic models." (PMID 29795450, 2018). "Regardless of the discrepancies, the analysis of a broad panel of 53 mediators suggests that IL-22, CCL22, and the IL-2/IL-4 ratio may aid in the diagnosis of PE and even in differentiating preeclampsia from gestational hypertension." (PMID 41156157, 2025). "The outcomes revealed that the expression levels of interleukin-4 and interleukin-13 pathway genes could significantly differentiate early preeclampsia from normal pregnancy." (PMID 37238928, 2023). "Regarding changes in the cytokine profile in preeclampsia, there is evidence that the levels of pro-inflammatory cytokines, namely TNF-α and IL-6, are increased in preeclampsia, while the concentrations of anti-inflammatory cytokines, namely IL-4 and IL-10, are decreased." (PMID 37168313, 2023).
preeclampsia (continued). "The present study aimed to examine the interleukin-13 and interleukin-4 pathway potential in the early detection of preeclampsia as well as the relationship between interleukin-13 rs2069740(T/A) and rs34255686(C/A) polymorphisms and preeclampsia risk to present a combined model." (PMID 37238928, 2023). "Furthermore, other studies suggest that IL-4 is significantly higher in preeclampsia compared to healthy pregnancy." (PMID 33680514, 2021). "Gene expression of anti-inflammatory IL-4 is low in preeclampsia." (PMID 26247971, 2015). "However, almost none of them directly mentioned the IL-13 and IL-4 signaling pathway; they suggested the genes connected to this pathway as being preeclampsia risk factors, initiators or progressors." (PMID 37238928, 2023). "On the other hand, the role of interleukin-13 (IL-13) and interleukin-4 (IL-4) pathway-related genes, such as STAT1, SOCS1 and JAK, in preeclampsia has been investigated." (PMID 37238928, 2023). "Decreased levels of anti-inflammatory cytokines (IL-10, IL-4) and increased pro-inflammatory cytokines (TNF-α, IL-6) in the circulation and placental tissue support the inflammatory background of preeclampsia." (PMID 35004644, 2021). "In preeclampsia, the proinflammatory : anti-inflammatory ratio (IL-2: IL-4 and IFN-γ : IL-4) is elevated compared to healthy pregnant controls, reflecting the more proinflammatory response associated with preeclampsia." (PMID 33680514, 2021). "It has been reported that a shift towards Th1-type immunity (increase in IL-2/IL-4 and IFN-γ/IL-4 ratios) in women with preeclampsia." (PMID 33224295, 2019). "Moreover, women with preeclampsia had significantly lower levels of IFN-gamma and IL-4 and significantly higher levels of IL-10 7 days later in comparison with the presenting levels." (PMID 28747200, 2017).
ulcerative colitis (24 papers, 2013 to 2025). An inflammatory bowel disease involving the mucosal surface of the large intestine and rectum. "Oxazolone, on the other hand, has been associated with IL-4 and IL-13 production and a Th2 immune response reminiscent of ulcerative colitis." (PMID 24376661, 2013). "Andrographolide can block the IL-4R-STAT6 pathway in the colon tissue of mice with ulcerative colitis, effectively inhibit the oxazolinone-induced inflammatory response; reduce inflammatory cell infiltration; and decrease the levels of IL-4, IL-13, and TNF-α." (PMID 36238575, 2022). "Jak3 knockout mouse model showing Il-2, Il-4, Il-7, Il-9, and Il-15 conduction defects, elevated levels of Il-6 and Il-17a and severe immunodeficiency, defects in barrier function lead to Ulcerative colitis (UC)." (PMID 33777833, 2021). "Currently, there is very little known about the involvement of IL-4/IL-13 signalling on smooth muscle cells in ulcerative colitis." (PMID 32410852, 2020). "Previous studies have highlighted a role for the Th2 cytokines IL-4 and IL-13 in mediating acute ulcerative colitis." (PMID 32410852, 2020). "On the other hand, the IL-4 and IL-5 cytokines involved in ulcerative colitis are secreted by Th2 cells." (PMID 30254638, 2018). "Interleukin (IL)-4 is a pleiotropic cytokine that is upregulated in certain types of inflammation, including IBDs and especially ulcerative colitis." (PMID 28316599, 2017). "A similar result has been showed in an ulcerative colitis model in which Dexamethasone increased the expression of IL-4." (PMID 28386549, 2017). "Andrographolide is able to lower the expression levels of IFN-γ, IL-23, and IL-17A in the peripheral blood mononuclear cells (PBMCs) of patients with ulcerative colitis, increase the expression of IL-4, inhibit the Th1/Th17 immune response and promote the Th2 response." (PMID 36238575, 2022). "Interestingly, GSK2256294 reduced IL4 and IFNγ in ulcerative colitis, and IL1β in Crohn's disease specifically, suggesting potential differential effects of GSK2256294 in these two diseases." (PMID 31002701, 2019). "Previous study found that IL-4 may be a cytokine that activates the high expression of inflammatory proteins and participates in the immune regulation of Th2 cells in patients with ulcerative colitis." (PMID 36941715, 2023). "Recently, treatment with LAB-fermented whey protein showed immunomodulatory effects by reducing the expression of IL-4 and TNF-α in an ulcerative colitis mouse model, demonstrating the potential of LAB-fermented proteins as novel immune-regulating therapies." (PMID 38062113, 2023). "Furthermore, IL-10 derived from B cells restrains the development of ulcerative colitis by suppressing T helper (TH) 2-type immune pathology and reduces the production of TH2 cell-mediated IL-4, which can trigger the disease." (PMID 29201923, 2017).